FAM111B (FAM111 trypsin like peptidase B)
Diseases named in the same sentence as FAM111B in open-access papers (continued):
Sharing a sentence is not in itself a finding about the gene and the disease.
glioma (continued). "Subsequent in vitro experiments confirmed that FAM111B overexpression enhanced the oncogenic properties of glioma cells, whereas its suppression inhibited these cellular processes." (PMID 40390043, 2025). "Collectively, these findings highlight the pivotal role of FAM111B in glioma pathogenesis." (PMID 40390043, 2025). "Furthermore, we assessed the protein expression of FAM111B in glioma cell lines (U251, U87, and SNB29) and in NHAs." (PMID 40390043, 2025). "Through enrichment analysis, we hypothesized that FAM111B influences glioma cell behavior by modulating the PI3K/AKT pathway." (PMID 40390043, 2025). "This study aimed to investigate the previously unknown role and molecular dynamics of FAM111B in gliomas." (PMID 40390043, 2025). "Consequently, our results suggest that FAM111B modulates the oncogenic properties of glioma cells via the PI3K/AKT pathway." (PMID 40390043, 2025). "Consequently, FAM111B has emerged not only as a critical biomarker for the development of glioma but also as a promising novel target for therapeutic intervention in glioma treatment." (PMID 40390043, 2025). "Collectively, these results support the hypothesis that FAM111B influences the malignant features of glioma cells primarily through the PI3K/AKT pathway, underscoring its potential as a regulatory factor in glioma pathogenesis." (PMID 40390043, 2025). "Time-dependent ROC analysis demonstrated that the area under the curve (AUC) values for predicting the 1-year, 3-year, and 5-year survival rates of glioma patients were 0.760, 0.811, and 0.776, respectively, highlighting FAM111B’s utility as a reliable biomarker for glioma diagnosis." (PMID 40390043, 2025). "Additionally, through both univariate and multivariate analyses, we established FAM111B as an independent prognostic indicator of gliomas." (PMID 40390043, 2025). "Consequently, FAM111B appears to be a significant contributor to glioma malignancy." (PMID 40390043, 2025). "FAM111B may be a predictive biomarker and a potential therapeutic target for gliomas." (PMID 40390043, 2025). "However, the expression and mechanistic involvement of FAM111B in gliomas, along with its impact on malignant tumor phenotypes, remain unclear." (PMID 40390043, 2025). "Our results showed that FAM111B expression was elevated in older patients, higher-grade gliomas (WHO III/IV), IDH-mutated gliomas, gliomas without 1p/19q codeletion, and patients with glioblastomas." (PMID 40390043, 2025). "Our findings revealed that FAM111B affected glioma malignancy by modulating the PI3K/AKT pathway, thereby presenting a new potential avenue for therapeutic intervention in the treatment of glioma." (PMID 40390043, 2025).
Gracile Bone Dysplasia (2 papers, 2015 to 2024). "FAM111A and FAM111B dysregulation are linked to genetic disorders: Kenny–Caffey Syndrome type 2 and Gracile Bone Dysplasia for FAM111A and POIKTMP, respectively, and cancers." (PMID 38474092, 2024).
prostate carcinoma (2 papers, 2019 to 2021). A carcinoma that arises from epithelial cells of the prostate gland. "FAM111B common variants are associated with prostate cancer susceptibility in the Japanese population." (PMID 31303963, 2019).
cholangiocarcinoma (1 paper, 2024). A carcinoma that arises from the intrahepatic biliary tree (intrahepatic cholangiocarcinoma) or from the junction, or adjacent to the junction, of the right and left hepatic ducts (hilar cholangiocarcinoma). "Additionally, a differential expression analysis of these genes based on cholangiocarcinoma and normal tissues samples from the TCGA database revealed significant upregulation of CDCA5, FAM111B, MCM8 and PCNA in cholangiocarcinoma, supporting their relevance in this context." (PMID 38687509, 2024).
colorectal cancer (1 paper, 2025). A primary or metastatic malignant neoplasm that affects the colon or rectum. "Our results showed that, in vitro, advanced glycation end products (AGEs) promoted CA, migration, and invasion of HCT116 colorectal cancer cells, with the highest CA level in the migrated cell fraction, and upregulated FAM111B, which promoted epithelial–mesenchymal transition." (PMID 41443421, 2025).
gastric cancer (1 paper, 2024). A primary or metastatic malignant neoplasm involving the stomach. "Moreover, an extensive pan-cancer analysis of FAM111B using datasets from cancer and gene expression databases and clinical cohorts of gastric cancer patients suggested including FAM111B as a prognostic biomarker for various cancers." (PMID 38474092, 2024).
laminopathies (1 paper, 2024). "It is worth noting that the abnormal nuclear shape (nuclear blebbing) in FAM111B defective cells recalls that observed in laminopathies, but the mutated FAM111B protease does not form a complex with lamins." (PMID 39273335, 2024).
lung disorder (1 paper, 2015). A disease involving the lung. "One specific example is FAM111B, an under-characterized gene associated with a human skin and lung disorder, whose expression pattern is remarkably similar to that of genes with functions in DNA replication." (PMID 26439921, 2015).
mucinous carcinomas (1 paper, 2025). "Our prior study revealed that FAM111B expression is elevated in serous carcinoma compared to mucinous carcinoma." (PMID 40564014, 2025). "FAM111B-positive cells (p = 0.0178), CD8+ T cells (p = 0.0245), CD4+ T cells (p = 0.0319), Tregs (p = 0.0178), CD4+ Teff cells (p = 0.0367), and DCs (p = 0.0140) were primarily enriched in other types of ovarian tumors relative to mucinous carcinomas." (PMID 40564014, 2025). "Additionally, the densities of FAM111B-positive cells (p = 0.0032), CD8+T cells (p = 0.0220), Tregs (p = 0.0041), and DCs (p = 0.0051) were also significantly higher in other ovarian tumor types compared to mucinous carcinoma samples." (PMID 40564014, 2025). "In tumor tissues, FAM111B-positive cells (p = 0.0068), CD8+ T cells, CD4+ T cells, Tregs, CD4+ Teff cells (all p < 0.0001), M2 macrophages (p = 0.0002), and DCs (p = 0.0004) were present at higher levels in serous carcinoma samples relative to mucinous carcinoma samples." (PMID 40564014, 2025).
pancreatic ductal adenocarcinoma (1 paper, 2025). An infiltrating adenocarcinoma that arises from the epithelial cells of the pancreas. "PRIM2 enhances FAM111B expression in pancreatic ductal adenocarcinoma, which in turn promotes tumor cell proliferation and migration." (PMID 40390043, 2025). "In pancreatic ductal adenocarcinoma, PRIM2 upregulates FAM111B expression, thereby enhancing RNA levels and protein stability." (PMID 40390043, 2025).
renal carcinoma (1 paper, 2024). A carcinoma arising from the epithelium of the renal parenchyma or the renal pelvis. "For instance, genes such as MYBL2, C7, FAM111B, LYVE, PKMYT, and HBB display comparable importance in classifying both breast and renal carcinomas." (PMID 39596491, 2024).
Rothmund-Thomson syndrome (1 paper, 2022). "Mutations in condon 628 of FAM111B identified in congenital poikiloderma were summarized." (PMID 36092869, 2022).
serous ovarian cancer (1 paper, 2025). "Immunohistochemical analyses conducted on tissue-microarray samples obtained from patients with serous ovarian cancer indicated that elevated levels of FAM111B expression were associated with unfavorable prognostic outcomes." (PMID 40781291, 2025). "Additionally, the elevated FAM111B expression was associated with poor prognosis of serous ovarian cancer patients." (PMID 40781291, 2025). "Combining the data on serous ovarian cancer and normal tissue samples from TCGA and GTEx databases revealed a significantly elevated level of FAM111B mRNA in serous ovarian cancer tissues compared to that in normal tissues." (PMID 40781291, 2025). "Survival analysis of 78 cases of serous ovarian cancer from tissue microarrays indicated that patients with high FAM111B expression possessed a significantly shorter median overall survival time compared to those with low expression (38 vs. 58 months; HR, 2.529; 95% CI, 1.110–5.762)." (PMID 40781291, 2025). "Elevated levels of FAM111B were also correlated with a negative prognosis in patients with serous ovarian cancer." (PMID 40781291, 2025).
stomach adenocarcinoma (1 paper, 2022). "Finally, pan-cancer mutation analysis showed that FAM111B and ZWINT had the highest mutation rates in u corpus endometrial carcinoma and stomach adenocarcinoma, respectively." (PMID 35406786, 2022).
cancer (23 papers, 2017 to 2025). A tumor composed of atypical neoplastic, often pleomorphic cells that invade other tissues. "Recent evidence demonstrates that FAM111B, which also has been referred to as a cancer-associated nucleoprotein, plays a crucial role in promoting various cancers, such as breast, lung, and pancreatic cancer (PC)." (PMID 40243892, 2025). "We evaluated its expression patterns in 33 cancer types and comprehensively assessed the FAM111B-associated pathways, which suggested mechanisms that are generalizable to many different cancer types." (PMID 40243892, 2025). "In our pan-cancer analysis, we demonstrated that FAM111B is linked to malignancy and poor prognosis, and that alterations in DNA repair and the immune microenvironment underlie the severity of diseases." (PMID 40243892, 2025). "While initially identified as the causative gene of POIKTMP, further research indicated that mutation or overexpression of FAM111B was linked to various types of cancers." (PMID 40781291, 2025). "The expression levels of FAM111B were elevated in most cancer types and were associated with poor prognostic outcomes." (PMID 40243892, 2025). "In cancer, FAM111B overexpression has been linked to tumor progression, potentially due to its involvement in DNA repair and cell cycle regulation." (PMID 38474092, 2024). "The overexpression and mutations of the FAM111B gene are associated with several types of cancers, including pancreatic cancer, which happens to be one of the most life-threatening types of cancer." (PMID 35860584, 2022). "The dysregulation of this protein ultimately leads to fibrotic diseases like POIKTMP and cancers via the disruption of these cellular processes by the mutation of the FAM111B gene." (PMID 35860584, 2022). "For instance, in cervical cancer patients, FAM111B, among other genes, is only overexpressed in later stages of cancer, and it is associated with distal cancer progression and metastasis." (PMID 35860584, 2022). "Based on these data, an EPB41L3-CUL7 axis promoted by FAM111B missense variants could potentially elucidate the susceptibility to cancer observed in individuals with POIKTMP." (PMID 40840166, 2025). "Certain cancers have been associated with microtubule instability, and this insight may aid in comprehending the involvement of FAM111B in processes like cell migration, proliferation and apoptosis." (PMID 38474092, 2024). "FAM111B, which encodes a protein containing a trypsin-like cysteine/serine peptidase domain, has been implicated in the progression of various human cancers; however, its involvement in BLCA remains unclear." (PMID 37958297, 2023). "In addition, the overexpression of FAM111B has been associated with cancer progression and poor prognosis." (PMID 35860584, 2022). "Further substantially downregulated genes include those encoding the transcription factor TCF19, which is associated with cancer cell survival and proliferation, and FAM111B, which encodes the DNA replication-associated serine protease F111B associated with both proliferation and cell cycle control." (PMID 34359681, 2021). "This study represents the first comprehensive analysis of FAM111B’s role in facilitating DNA damage repair and modulating tumor immunity within a pan-cancer context." (PMID 40243892, 2025). "In summary, this study represents the first demonstration that FAM111B facilitates cancer progression by modulating DNA repair processes, particularly HR repair in various cancers." (PMID 40243892, 2025). "In this study, we conducted a pan-cancer analysis using TCGA data to investigate FAM111B’s role in DNA damage repair and the immune microenvironment across cancers." (PMID 40243892, 2025).
cancer (continued). "Family with sequence similarity 111 member B (FAM111B) is highly expressed in multiple cancer types and is designated as a cancer nuclear protein." (PMID 40564014, 2025). "Other regulatory mechanisms of FAM111B are anticipated to participate in its oncogenic functions across various cancer types." (PMID 40781291, 2025). "To evaluate pan-cancer FAM111B expression, we analyzed RNA-seq data from healthy controls and patients with 31 types of cancer from the TCGA and GTEx datasets." (PMID 40243892, 2025). "Recent evidence indicates that FAM111B is significantly involved in the progression of various cancers." (PMID 40243892, 2025). "The findings of this study indicate the potential therapeutic significance of inhibiting FAM111B in cancers that exhibit elevated FAM111B expression." (PMID 40781291, 2025). "We focused on a family with sequence similarity 111 member B (FAM111B) and investigated its cancer-promoting functions in LUAD cells." (PMID 39337462, 2024). "FAM111B is generally a cancer-promoting gene in most tumor types, with the exception of its ability to suppress PTC." (PMID 37958297, 2023). "Given the possible involvement of FAM111B in DNA repair, the overexpression of the FAM111B gene can support cancer progression." (PMID 35860584, 2022). "However, this study is the first to evaluate the role of FAM111B in mediating DNA repair mechanisms across cancers." (PMID 40243892, 2025). "FAM111B, a trypsin-like serine protease, initially studied in cancer, exhibits germline variants not consistently linked to tumours, suggesting broader functions beyond cell proliferation." (PMID 40840166, 2025). "Therefore, our findings are consistent with the established role of FAM111B in modulating the immune environment to promote cancer progression." (PMID 40243892, 2025). "Furthermore, functional analysis of FAM111B suggested that aberrant expression of FAM111B had cancer-promoting functions such as promoting the cell cycle progression and inhibition of apoptosis." (PMID 39337462, 2024). "Thus, FAM111B is an oncogene associated with BLCA and holds promise as a molecular target for future treatment of this cancer." (PMID 37958297, 2023). "This might be consistent with the increased cancer susceptibility observed in POIKTMP patients, if hyperactivation of FAM111B exhibits gain-of-function effects." (PMID 36589246, 2022). "Altogether, the correlation of high FAM111B with poor survival in several cancer types suggests that it may be an oncogene." (PMID 36589246, 2022). "FAM111B overexpression is connected to poor prognosis and progression in cancers." (PMID 36589246, 2022). "This implies that FAM111B mutations not only cause the multisystemic phenotypes observed in POIKTMP patients, but also might promote cancer formation." (PMID 36589246, 2022). "FAM111B may shape the advancement of various cancers by participating in the regulation of the cell cycle, influencing the metabolism of cancer cells, taking part in DNA damage repair, suppressing cellular apoptosis and facilitating epithelial–mesenchymal transition." (PMID 40564014, 2025). "Cancer and non-cancer-associated FAM111B mutations have also been reported." (PMID 38474092, 2024). "Our siRNA-mediated knockdown assays demonstrated that downregulation of FAM111B significantly inhibited cancer cell proliferation, migration, invasion abilities, and induced cell cycle arrest and apoptosis, and strongly suggested as a cancer-promoting gene in LUAD cells." (PMID 39337462, 2024). "Moreover, the heightened expression of FAM111B in cancer could potentially impact the dynamics of spindle microtubules, a crucial component in cell division." (PMID 38474092, 2024). "MET, AM25C, MROH9, MYEOV, FAM111B, Y6D, and PPP2R3A were highly expressed in the high-risk group, indicating that these genes may be related to the oncology process for patients with PAAD, and they seemed to be cancer-promoting genes." (PMID 35077391, 2022).